BECN1 (beclin 1)
Diseases named in the same sentence as BECN1 in open-access papers (continued):
Sharing a sentence is not in itself a finding about the gene and the disease.
infection (continued). "Our study showed that the expression of autophagy-related genes ULK1, ATG13, ATG101, Beclin-1, ATG14, MAP1LC3A, and MAP1LC3B was significantly increased and that SQSTM1 was decreased in the muscle with pathogen infection." (PMID 33574492, 2021). "UPEC infections increase RhoB, Beclin 1 and LC3 levels in bladder epithelium in vivo, whereas Beclin 1 and LC3 levels as well as UPEC clearance are substantially reduced in RhoB+/− and RhoB−/− mice upon infection." (PMID 33972537, 2021). "The survival rates in pregnant dams’ post-infection with ZIKV was also monitored for the duration of gestation and showed minimal differences between mock- (PBS) and ZIKV-infected Becn1+/+ dams when compared to similar treated Becn1+/− dams." (PMID 32498399, 2020). "The phagophores undergo nucleation and elongation with Beclin-1/Vps34 complex and LC3 lipidation to form double-membraned autophagosomes, and the autophagic membranes generated during infection are used for viral envelopment." (PMID 32878239, 2020). "The infection with Ad-26b-5p, Ad-204-5p, and Ad-497-3p significantly decreased the IGF-1-induced expression of LC3 II and Beclin 1 proteins in cardiomyocyte hypertrophy (P < 0.01)." (PMID 32140172, 2020). "BECN1 and ATG3 mRNA were significantly increased after 24 h post-infection (hpi) as compared to their respective uninfected controls." (PMID 32512864, 2020). "Stimulation of human macrophage-like cells with the P90A virus protected them against subsequent infection with an otherwise resistant wild type HIV-1 in a manner requiring TRIM5α, BECN1, and ULK1." (PMID 33052966, 2020). "In the early stage of infection, the viral protein NS1 prevents Beclin-1 from cleavage to maintain autophagy, which inhibits early apoptosis and increases viral replication." (PMID 33352639, 2020). "The kinetics for Beclin-1 and LC-3B were similar to NIH:Swiss with peak responses between 9-12 days while p62 remained elevated even at day 19 post-infection." (PMID 31040926, 2019). "To test the effects of overexpression of CFTR in hepatocytes on the expression of autophagy-related proteins p62, BECN1, LC3, and Atg12, we detected their expression after infection." (PMID 29415998, 2018). "To determine which autophagy proteins mediate BTZ resistance, we rescued LAMP-1, Beclin 1, and LC3B expression in ARP-1 cells by infection with lentivirus containing human LAMP1, Beclin-1, or LC3B ORFs, respectively." (PMID 25895124, 2015). "Upon NDV/FMW infection, the expression of beclin-1 in A549/DDP cells was nearly unchanged from 4 to 12 hpi and was completely diminished at 24 hpi, suggesting that NDV/FMW infection decreases beclin-1 expression in the late stage of infection." (PMID 25078870, 2014). "The specificity of genetic knockdowns of mTOR, Beclin-1 and Atg7 have confirmed that HPV-induced restraint of autophagy is important for early infection events." (PMID 25202355, 2014). "Furthermore, BECN1 overexpression significantly suppressed the production of IFN-α and IFN-β in BVDV-infected BT cells compared with infection alone (P < 0.01)." (PMID 41363843, 2026). "Levels of WIPI1 and Beclin-1 expression were increased by the autophagy inducer torin but were no different in SFV-infected cells early in infection." (PMID 40042894, 2025). "We also investigated the impact of VgrG2 on the mTOR signaling pathway by examining the transcription levels of key genes, including mTOR, ULK1, Beclin-1, P62, LC3, Atg3, Atg5, and Atg12, following infection, and assessed the expression of the autophagy marker protein LC3-II." (PMID 40266908, 2025). "This indicates that S. Typhimurium activates the pathway upstream of BECN1 in Becn1F121A epithelial cells and that constitutive autophagy is independent of infection." (PMID 39602254, 2024).
infection (continued). "Most viruses recognize pathogen-associated molecular patterns (PAMPs) via pattern recognition receptors (PRRs) during infection of host cells; in mammals, the endosomal TOLL-like receptor is predominant, which stimulates downstream junctions to interact with BECN1, activating autophagy." (PMID 38247875, 2024). "After 4 weeks post-infection, approximately 978 RNA copies/mL were detected in the serum recovered from the C57BL/6J control mice and about 1014 RNA copies/mL in the serum recovered from the Becn1+/− mice." (PMID 37766329, 2023). "Previous reports did not clarify the mechanism of BECN1 downregulation through infection with these bacteria." (PMID 37740192, 2023). "The importance of LC3B reduced expression on infection outcome was highlighted by the infection rate increase in LC3B- but not in BECN1-silenced THP-1 cells." (PMID 37064813, 2023). "The infection influenced the expression level of Beclin 1, both under normoxia and hypoxia, similarly as did LPS." (PMID 35755850, 2022). "There were no marked changes noted in the expression of Becn1, Atg5, Atg7, Atg12, Atg16l1 or Atg16l2 both before and 6 h after infection." (PMID 35903351, 2022). "In the present study, BECN1 expression was significantly upregulated in the liver in the high omega-3NPs supplemented group post infection more than challenged-non-supplemented group indicated their role in initiating autophagy-related genes." (PMID 36009242, 2022). "As for SQSTM1 and BECN1, there was no change in transcription at 24 h post-infection, but there was a noticeable increase at 48 h post-infection." (PMID 36298785, 2022). "When autophagy in MRC5 was chemically inhibited, infection with MERS-CoV-MA-WT did not induce further changes in BECN1, ATG3 or LC3A mRNA levels, as compared to non-treated cells (WT columns)." (PMID 36129908, 2022). "To confirm the absence of regulation of major genes involved in the autophagic machinery, we verified the expression of two key genes, BECN1 (involved in autophagic vacuole formation) and ATG3 (involved in the ubiquitination process) during the course of infection." (PMID 34835061, 2021). "Autophagy is the suicidal mechanism that an infected cell adopts to protect adjacent cells from further infection., When SARS-CoV-2 infects a cell, the virus will forestall the autophagy mechanism by releasing SKP2 protein that can inhibit the cell’s Beclin-1 production." (PMID 34961070, 2021). "Infection with PMM127 induced an approximately two-fold increase in the Beclin-1 protein amount compared to WT Mtb and noninfected macrophages." (PMID 32182946, 2020). "Moreover, inhibition of caspase activity not only reduced Beclin-1 cleavage but also increased LC3-II accumulation and viral titers by 0.85 logs (p < 0.05) at 48 h post-infection." (PMID 33352639, 2020). "We next generated ULK1, BECN1, and ATG7 THP-1 cell lines to test whether HIV-1 CA P90A infection could similarly induce the expression of pro-inflammatory genes in cells lacking autophagy." (PMID 33052966, 2020). "Additionally, during permissive infection, HIV Nef binds to Beclin 1, a key protein in autophagy, resulting in the down-regulation of autophagy that can lead to the prevention of autolysosomal degradation of the virus." (PMID 31142734, 2019). "Infection of VeroB4 cells with MERS-CoV facilitated increased phosphorylation of SKP2 at S72, with a concomitant decrease of cellular levels of BECN1 and enhanced K48-polyubiquitinylation of BECN1." (PMID 31852899, 2019). "In addition to NIH:Swiss outbred mice, colons of C57Bl/6 inbred mice also exhibited elevated levels of Beclin-1, LC3B and p62 staining in response to CR infection." (PMID 31040926, 2019). "During measurement of Beclin-1, LC3B and p62 kinetics in Apc++ NIH:Swiss mice, the staining intensities for these proteins increased significantly at day 12 and subsequently declined at days 20, 27 and 34 post-infection." (PMID 31040926, 2019).
infection (continued). "Our data showed that the levels of p-JNK, p-Bcl-2, LC3-II and DENV2 NS1 proteins evidently increased, but the expression levels of Bcl-2 and BECN1 were not significantly changed at 36 h post DENV2 infection (lane 1 vs. lane 2)." (PMID 29323257, 2018). "Furthermore, the percentage of EEA1- and Rab7-positive compartments containing GAS in Beclin 1 and UVRAG KO cells decreased significantly, compared to that in wild-type cells during infection." (PMID 30488027, 2018). "We found that the amount of d ATG12 mRNA increased about 3.5-fold by R38AK41A infection but not Beclin-1 mRNA." (PMID 30619194, 2018). "To further explore whether AMPK regulates BECN1 and other molecules, such as ACSL4 or GPX4, in the context of CAP-induced ferroptosis, we constructed a stable cell line with AMPK knockdown through lentivirus-mediated shRNA infection." (PMID 40438695, 2025). "The upregulation of miR-30a-3p during infection has been reported to be a trigger for L. donovani, which is characterized by the suppression of the autophagic process in THP-1 and human monocyte-derived macrophages by the negative regulation of Beclin-1 (BECN1)." (PMID 38390455, 2023). "Furthermore, a decrease infectivity of L. donovani due to the inhibition of the autophagic mechanism via negative regulation of Beclin 1 (BECN1) in THP-1 and human monocyte-derived macrophages has been reported to be triggered by the upregulation of miR-30a-3p during infection." (PMID 33178551, 2020). "Interestingly, although there is no change of Beclin-1 expression from 12 to 24 h post-infection, a decrease in the full length of Beclin-1 (around 60 kDa) and an increase in cleavage forms (around 50 and 40 kDa) were notable at 48 h post-infection." (PMID 33352639, 2020). "Our findings demonstrate both in an in vitro model and ex vivo studies that NP-Beclin 1 and NP-vFLIP-α2 can induce the selective killing of latent HIV-infected resting memory CD4+ T cells, while sparing uninfected cells and preventing new infection of bystander cells." (PMID 31142734, 2019). "In addition, infection of cagA+/vacAs1m2 strains was significantly associated with increased levels of mRNA expression of SQSTM1, but not of BECN1." (PMID 28983474, 2017). "It should be noted that during the course of the respective antigen presentation experiments (48 hpi), siRNA-mediated silencing of Beclin-1 and Atg7 did not affect expression and/or infection-dependent induction of surface MHC I (H-2Kb and H-2Db), CD80, CD86, PD-L1 or PD-L2." (PMID 28634388, 2017). "However, by 3 weeks post-infection, beclin 1 knockdown resulted in a significant decrease in the number of surviving MAP2+ neurons, supporting previous findings that neurons with decreased levels of beclin 1 degenerate in vivo." (PMID 26692002, 2015). "We found that beclin-1 expression was up-regulated in a time-dependent manner in NDV-infected A549/PTX and parental cells, suggesting that beclin-1 may participate in the induction of autophagosome formation in these cells during NDV/FMW infection." (PMID 25078870, 2014). "Interestingly, we found that nuclear fragmentations typical for apoptosis following MV-Edm infection occurred exclussively in autophagy knockdown cells treated with ATG7, BECN1 and SQSTM1 siRNA, respectively, whereas nuclei within syncytia remained intact in control siRNA treated cells." (PMID 25004098, 2014). "To elucidate whether BVDV-induced upregulation of BECN1 influences the RIG-I-like receptor (RLR) signaling pathway, we examined the expression of key proteins in the RIG-I pathway in BT cells with either overexpression or knockdown of BECN1 after cp/ncpBVDV infection." (PMID 41363843, 2026). "Interestingly, the infection frequency of the knock down cell lines was approximately 2-fold higher than the scrambled control (data not shown) suggesting that Beclin-1 activity may modestly impair F. tularensis infection of host cells." (PMID 23966861, 2013).
infection (continued). "Restoration of autophagy flux was dependent on the absence of 4b during infection, since the presence of 4b in MERS-CoV-MA-WT infected cells prevented the recovery of BECN1, ATG3 or LC3A mRNA levels." (PMID 36129908, 2022). "We also found that the expression of markers, Beclin 1 and LC3B, involved in autophagy activity were appropriately decreased with the treatment of 07-IgG1 in the EV-A71 mice infection model (data not shown)." (PMID 35130884, 2022). "Whereas infection of control THP-1 macrophages with HIV-1 CA P90A increases the expression of IFNB1, this effect is not seen in ULK1, BECN1, or ATG7 knockout THP-1 cells." (PMID 33052966, 2020). "In all three muscles, infection induced increases in p62/SQSTM1 and BNIP3 protein levels, but exerted no influence on BECN1 or PI3KC3." (PMID 28659735, 2017). "Immunofluorescence confocal microscopy analysis and quantification show that ~80% of mycobacteria are decorated with Beclin-1 and Atg16L1 but not with ULK1 at 2 h post-infection." (PMID 27242971, 2016). "Simultaneously, the clinicopathological significance of negative Beclin-1 and LC3B expression in cervical SCC with hrHPV infection was investigated." (PMID 25202355, 2014). "The requirement of autophagy-initiation proteins ULK1, Beclin 1, and ATG14L and PI3-kinase activity but not elongation proteins ATG5, ATG16L1, ATG4B, ATG7, and LC3B suggested Brucella selectively co-opts autophagy-initiation complexes to subvert host clearance and promote infection." (PMID 38376367, 2024).
neurodegenerative disease (27 papers, 2012 to 2025). A disorder of the central nervous system characterized by gradual and progressive loss of neural tissue and neurologic function. "Further studies have found that the expression of Beclin-1 is significantly reduced in Beclin-1-deficient transgenic mice, which leads to a decrease of autophagy in neurons which is the reason for neurodegenerative diseases." (PMID 35662922, 2022). "Our data demonstrate a dual role for Beclin 1 in both neuronal cell loss and neuroprotection, making it an interesting target for future therapeutic interventions to treat neurodegenerative diseases." (PMID 30594228, 2018). "Cellular levels of beclin-1 are often correlated with autophagic activity as the reduced expression in neurodegenerative diseases is linked to autophagy impairment." (PMID 27328712, 2016). "Deficiency of autophagy protein beclin 1 is implicated in tumorigenesis and neurodegenerative diseases, but the molecular mechanism remains elusive." (PMID 25275521, 2014). "Our study therefore provides genetic proof for a previously poorly understood function of beclin 1 and expands our knowledge regarding various beclin 1-associated pathogenic mechanisms including those of tumorigenesis and neurodegenerative diseases." (PMID 25275521, 2014). "BECN1 regulates autophagy initiation; dysregulation may result in neuron damage and an increased risk of neurodegenerative diseases." (PMID 40313396, 2025). "Given the potential functional implications of Beclin 1 cleavage, the question arises whether the involvement of Beclin 1 in neurodegenerative diseases extends beyond the loss of its canonical role in autophagy and clearance of protein aggregates." (PMID 30594228, 2018). "It is this duality of Beclin 1 function inherent in its cleavage state that positions Beclin 1 as an attractive candidate to be explored as a potential therapeutic target aimed at combating neuronal cell loss in a variety of neurodegenerative diseases by preventing its proteolytic cleavage." (PMID 30594228, 2018). "Furthermore, although beclin 1 has been linked to multiple neurodegenerative diseases, the function of beclin 1 in the brain remains uncharacterized." (PMID 25275521, 2014). "Along with these illnesses, there is substantial evidence of autophagy dysregulation in neurodegenerative diseases, such as alterations in mTOR and beclin 1 expression, and accumulation of defective autophagosomes." (PMID 32679743, 2020). "To begin to investigate the functional role of Beclin 1 cleavage in the context of a neurodegenerative disease we sought to utilize existing mouse models exhibiting robust neuronal cell loss." (PMID 30594228, 2018). "Because beclin 1 functions in both autophagy and protein sorting, it represents an intriguing therapeutic target for neurodegenerative disease." (PMID 26692002, 2015). "Knowledge of both the autophagy and protein sorting functions of beclin 1 should inform strategies to target beclin 1 in neurodegenerative disease." (PMID 26692002, 2015). "Our study clarifies the physiological function of beclin 1, which leads for further understanding of its role in tumorigenesis, infectious disease and neurodegenerative disease." (PMID 25275521, 2014). "Together, these studies suggest that beclin-1 is an important regulator in neurodegenerative diseases." (PMID 23300858, 2012). "However, it has been reported previously that elevated beclin-1 levels can occur in response to the presence of toxic protein species and therefore a requirement for autophagy induction in models of neurodegenerative diseases." (PMID 36980234, 2023). "Thus, the Becn1+/− mice can be considered as an adequate model of mild deficit in autophagy, which can occur, for instance, during the early stages of age-related neurodegenerative diseases." (PMID 36012495, 2022).
neurodegenerative disease (continued). "To determine whether Beclin 1 cleavage occurs in the context of a neurodegenerative disease we performed Western blot analysis on the RIPA-soluble fraction of cortical brain lysates from AD patients and healthy controls." (PMID 30594228, 2018). "BECLIN-1 deficiency has been characterized in several pathological conditions and enhancing autophagy, for example with the Tat-BECLIN-1 construct, has been presented as a potential route for valuable therapeutic applications, notably in neurodegenerative diseases." (PMID 30319621, 2018). "Similarly, Beclin-1, which plays a key role in autophagy initiation through complex formation with PI3K, is positively regulated upon GSK3β inhibition, restoring autophagic activity and reducing neuronal loss in neurodegenerative disease models." (PMID 41190025, 2025). "Interestingly, other BECN1 activators, such as Tat‐BECN1 and Isorhynchophylline, have also been identified to play a neuroprotective role in preclinical studies, which indicates the great potential of BECN1‐depedent autophagy in treatment of neurodegenerative diseases." (PMID 35845350, 2022). "Similarly, targeting GSK3β to restore Beclin-1 expression and LC3B-II conversion in neuronal models may offer a translatable strategy for neurodegenerative diseases, where impaired autophagic flux is a major pathological driver." (PMID 41190025, 2025). "Through the use of a viral-mediated overexpression approach in conjunction with two neurodegenerative disease mouse models, we were able to tease apart the individual role of each Beclin 1 cleavage fragment in neurodegeneration with and without protein aggregation." (PMID 30594228, 2018).